CDK5 (cyclin dependent kinase 5)
Diseases named in the same sentence as CDK5 in open-access papers (continued):
Sharing a sentence is not in itself a finding about the gene and the disease.
Alzheimer disease (continued). "The evaluation of these molecules as inhibitors on a mammalian kinases panel revealed that several compounds (5, 6, 10 and 11) exhibit marked activities against CDK5, CK1 and DYRK1A, a set of kinases involved in several neuronal pathologies such as Down Syndrome and Alzheimer’s disease." (PMID 25251193, 2014). "Since apoE is important in the pathogenesis of Alzheimer's disease (AD), we tested whether apoE treatment of neurons affected molecules important to phosphorylation of tau, such as GSK 3β, P35, and CDK5, and the phosphorylation of tau itself." (PMID 17166269, 2006). "↓ of kinase expression (5 μM): GSK3β, CDK5, DYRK1A, CAMK2A, MAPK1, MAPK12, MAPK14.Modulation of the hGMSC transcriptome, ↓ expression of genes involved in Alzheimer's pathogenesis.↓ expression of GSK3b and p‐GSK303B2, which plays a key role in Alzheimer's disease." (PMID 39653426, 2025). "Therefore, safe and effective studies suggest that the BACE1 and CDK5 RNAi-based therapy would be ready for a potential translational trial in a patient with advanced or mild stage of Alzheimer disease, without additional option for a curative treatment." (PMID 28066230, 2016). "However, APP, Presenilin1/2, tau, Apolipoprotein E, Cdk5, TDP-43 or GSK-3beta, which are implicated in Alzheimer's disease and tauopathy, were not included in these results." (PMID 21731734, 2011). "Moreover, EGR-1 is up regulated in brain of patients with Alzheimer disease (AD), and overexpression of EGR-1 controls both phosphorylation and dephosphorylation of tau, by activating CDK5 and inactivating PP1, leading to tau hyperphosphorylation and destabilized microtubules." (PMID 24066134, 2013).
Parkinson disease (57 papers, 2012 to 2025). A progressive degenerative disorder of the central nervous system characterized by loss of dopamine producing neurons in the substantia nigra and the presence of Lewy bodies in the substantia nigra and locus coeruleus. "MEF2D is also linked to Parkinson’s disease through the cyclin-dependent kinase 5 (Cdk5), which directly phosphorylates MEF2D at Ser444." (PMID 36834528, 2023). "CDK5 has been most extensively characterized in the nervous system and has been implicated in the pathogenesis of Alzheimer’s and Parkinson’s diseases." (PMID 35514210, 2022). "Cdk5 plays a critical role in the CNS during development, and its over-activation is linked to neurodegeneration following AD, Parkinson’s and Huntington’s diseases." (PMID 32046281, 2020). "Cdk5-mediated phosphorylation of EndoB1 insured neural loss due to autophagy induction in models of Parkinson’s disease." (PMID 31698798, 2019). "Deregulation of Cdk5 results in neuronal loss in Parkinson’s, Alzheimer’s and Huntington’s diseases, which underscores the importance of the complex regulation of Cdk5 activity necessary to maintain its activity within physiological levels." (PMID 29225566, 2017). "Our data indicate that Parkinson-related LRRK2 mutation R1628P leads to Cdk5 phosphorylation of LRRK2 at S1627, which would upregulate the kinase activity of LRRK2 and consequently cause neuronal death." (PMID 26930193, 2016). "Cdk5 plays a pivotal role in the CNS development, and Cdk5 dysregulation has been implicated in different pathologies including Alzheimer's and Parkinson's disease." (PMID 25760945, 2015). "While Cdk-dependent phosphorylation of Prdx has been more comprehensively detailed for Prdx1, evidence of Prdx2 targeting by Cdk5/p35 and Cdk5/p25 complexes was described to reduce peroxidase activity and cause neuronal death in a toxin-induced model of Parkinson’s disease." (PMID 30678096, 2019). "Also, association of CDK5 with p25 leads to altered regulation of CDK5 that promotes neuronal apoptosis and development of neurological diseases such as Alzheimer’s and Parkinson’s disease." (PMID 31698798, 2019). "However, exaggerated Cdk5 is implicated in different types of neurodegenerative diseases including Parkinson disease (PD)." (PMID 38842132, 2024). "Serum levels of CDK5 also decreased in patients with Parkinson’s disease accompanied by motor symptoms." (PMID 37223477, 2023). "The specific targets of miR-188-3p have been identified as NOD-like receptors 3 (NLRP3) and cyclin-dependent kinase 5 (Cdk5), signifying its promising potential as a therapeutic target in Parkinson’s disease (PD)." (PMID 38004615, 2023). "Irregular Cdk5 activation and its phosphorylation of substrates as tau, MAP2, and MAP1b have been associated with pathological conditions, such as Alzheimer and Parkinson’s diseases." (PMID 35182267, 2023). "Phosphoproteomics has also revealed that aberrant p25/Cdk5 signaling occurs in early-stage Parkinson’s disease in α-synuclein transgenic mice, whereas PINK1 regulates a subset of Rab GTPases." (PMID 37179123, 2023). "In fact, Cdk5 is implicated in neurodegenerative diseases such as Alzheimer’s disease (AD) and Parkinson disease (PD) by contributing to the formation of the aberrantly phosphorylated tau protein and to the degeneration of dopaminergic neurons in the substantia nigra." (PMID 36142566, 2022). "CDK5 hyperactivity has been described in several neurodegenerative disorders including Alzheimer's and Parkinson's disease as well as amyotrophic lateral sclerosis (ALS)." (PMID 32974274, 2020). "CDK5 has long been considered a relevant pharmacological target in neurodegenerative diseases (Alzheimer's, Parkinson's, Huntington's, ALS) and has more recently become an attractive drug target for cancer therapy." (PMID 32974274, 2020). "CDK5RAP1 is a repressor of CDK5, which is a cyclin-dependent protein known to be involved in neurodegenerative diseases like Parkinson’s and Alzheimer’s." (PMID 30096876, 2018).
Parkinson disease (continued). "In Parkinson’s disease (PD) Sirt1 level is down-regulated by Cdk5 through ubiquitin-proteasome pathway that is up-regulated." (PMID 30304806, 2018). "The connection between MEF2D and Parkinson's disease started with the finding that cyclin dependent kinase 5 (Cdk5) directly phosphorylates MEF2D at Ser444 under stress conditions, which leads to an impairment of MEF2D transcriptional function." (PMID 27413575, 2016). "Indeed, SPL was shown to directly regulate protein stability and/or ubiquitination in a cyclin-dependent kinase 5 (Cdk5)-dependent manner in Parkinson’s disease." (PMID 36678589, 2023). "Cdk5 is known to be involved in neuronal differentiation, and its aberrant activity contributes to the pathogenesis of neurodegenerative disorders, including amyotrophic lateral sclerosis and Huntington’s, Alzheimer’s, and Parkinson’s diseases." (PMID 35203613, 2022). "CDK5/p25 kinase plays a major role in neuronal functions, and is hyperactivated in several human cancers including glioblastoma and neurodegenerative pathologies such as Alzheimer's and Parkinson's." (PMID 32974274, 2020). "Importantly, Cdk5-mediated phosphorylation of Endophilin B1 appeared necessary for the elimination of dopaminergic neurons in an MPTP mouse model of Parkinson's disease." (PMID 29227247, 2017). "Pathological Cdk5 activation is believed to contribute to Parkinson’s disease." (PMID 29227247, 2017). "Therefore, it is reasonable to speculate that Cdk5 can become a therapeutic target for melanoma and even for neurodegenerative pathologies such as Alzheimer’s and Parkinson’s diseases." (PMID 29062096, 2017). "Moreover, CDK5 participates in the hyperphosphorylation of alpha-synuclein and parkin, thereby contributing to generation of Lewy bodies in Parkinson’s disease and to Lewy bodylike inclusions, which ultimately contribute to neuronal loss in amyotrophic lateral sclerosis." (PMID 25625291, 2015). "Several studies have shown that CDK5 is hyperactivated by p25 in Alzheimer’s disease, amyotrophic lateral sclerosis (ALS), and Parkinson’s disease." (PMID 25625291, 2015). "Meanwhile, CDK5 mediates nuclear translocation Sirtuin 2 (SIRT2) by directly phosphorylating SIRT2 residues, thereby promoting the death of dopaminergic neurons in a mouse model of Parkinson's disease." (PMID 36964998, 2023). "Wen and colleagues showed that CDK5 (Cyclin Dependent Kinase 5)-mediated phosphorylation of RKIP on T42 residue triggers recruitment of the chaperone molecule Hsc-70 and subsequent autophagy-mediated degradation of RKIP in Parkinson disease." (PMID 30181452, 2018). "Moreover, plasma MALAT1, miR-125b, FOXQ1, PTGS2, and CDK5 could distinguish AD patients from controls, while only plasma MALAT1, miR-125b, and PTGS2 could discriminate AD patients from Parkinson’s disease patients." (PMID 36947499, 2023).
breast carcinoma (53 papers, 2010 to 2025). "Loss of CDK5 in breast cancer cells opens up the mitochondrial permeability transition pore (mPTP), initiating increased mitochondrial depolarization and higher ROS levels, with subsequent activation of caspases and cell death." (PMID 37993880, 2023). "CDK5 also localizes on the inner mitochondria membrane, and loss of CDK5 in breast cancer cells was reported to promote ROS accumulation through dysregulation of the mitochondrial permeability transition pore." (PMID 37511490, 2023). "In breast cancer, low Cdk5 expression has also been shown to be associated with adverse survival of breast cancer patients." (PMID 33991172, 2021). "In this study, we explored associations between PKA, PP1, DARPP‐32 and Cdk5 expression and breast cancer–specific survival." (PMID 33991172, 2021). "Associations between combined PKA, PP1, DARPP‐32 and Cdk5 expression and breast cancer–specific survival were assessed." (PMID 33991172, 2021). "In previous studies, we demonstrated that low DARPP‐32 and Cdk5 expression is associated with adverse survival of breast cancer patients." (PMID 33991172, 2021). "We now know that loss of Cdk5 in breast cancer cells causes increased mPTP opening that is associated with mitochondrial depolarization, increased ROS levels, mitochondrial fragmentation and apoptosis." (PMID 32024968, 2020). "In breast cancer, high expression of Cdk5, determined by immunoblotting, is associated with ER‐negative tumours and basal‐like tumours in 108 patients; however, no information on survival was available in this study." (PMID 32352232, 2020). "We previously demonstrated that loss of Cdk5 in breast cancer cells promotes ROS-mediated cell death by inducing mitochondrial permeability transition pore (mPTP) opening (Oncogene 37, 1788–1804)." (PMID 32024968, 2020). "Low nuclear and cytoplasmic expression of Cdk5 expression was significantly associated with shorter breast cancer‐specific survival (P = .004 and P = .001, respectively)." (PMID 32352232, 2020). "We previously reported that loss of Cdk5 promotes mitochondrial permeability transition pore (mPTP)-mediated apoptosis in breast cancer cells." (PMID 32024968, 2020). "In breast cancer, while CDK5 inhibition causes the depolymerisation and the rearrangement of F-actin, CDK5 upregulation potentiates F-actin bundles." (PMID 33396266, 2020). "Both low nuclear and cytoplasmic expressions of Cdk5 were associated with adverse breast cancer‐specific survival (P = .004 and P = .001, respectively)." (PMID 32352232, 2020). "Previously, we demonstrated that knocking down Cdk5 by siRNA in breast cancer cells causes mPTP opening and subsequent ROS increase, which promotes cell death." (PMID 32024968, 2020). "A number of studies have assessed levels of CDK5 mRNA and associations with survival in breast cancer." (PMID 32352232, 2020). "It is interesting, however, that while loss of Cdk5 in breast cancer cells promote apoptosis, we observed that Cdk5−/− MEFs show increased proliferation (data not shown)." (PMID 32024968, 2020). "CDK5 was implicated to protect breast cancer cells against reactive oxygen species (ROS)-mediated apoptosis." (PMID 31910742, 2020). "In the current study, we demonstrate that, in a large cohort of breast cancer patients, low nuclear and cytoplasmic expression of Cdk5 is significantly associated with adverse disease‐specific survival (P = .004 and P = .001, respectively)." (PMID 32352232, 2020). "In the current study, low CDK5 mRNA expression is associated with shorter breast cancer‐specific survival of a large well‐annotated cohort of breast cancer patients (P = .005)." (PMID 32352232, 2020). "Tamoxifen (TMX), which is an endocrine treatment for breast cancer, has been reported as a new inhibitor of CDK5 kinase activity by interrupting the association between CDK5 and its activator p35/p25." (PMID 31272499, 2019).
breast carcinoma (continued). "Our previous study demonstrated that the aberrant activation of CDK5 signaling is associated with lymph node metastasis in breast cancer, which was responsible for high-dose taxol-induced invasion and EMT." (PMID 29325547, 2018). "Loss of Cdk5 has been demonstrated to act in breast cancer cells by increasing their sensitivity to drug therapy due to dysregulation of mPTP-dependent mitochondrial functions causing intrinsic apoptosis through increased ROS production and caspase activation." (PMID 30011966, 2018). "And in some studies, CDK5 was associated with the development of several cancers, such as lung cancer, breast cancer, prostate cancer and neuroendocrine thyroid cancer." (PMID 27406233, 2016). "In breast cancer, miR-21/CDK5 axis was abnormal activated which had an association with lymph node metastasis." (PMID 27406233, 2016). "In breast cancer, CDK5 is often overexpressed and associated with poor prognosis." (PMID 39800748, 2025). "Similarly, CDK5 hyperactivation upon neurotoxic insults causes mitochondrial dysfunction leading to cell death in AD, whereas in breast cancer, loss of CDK5 has the same impact." (PMID 37993880, 2023). "We found that Cdk5 loss induces mPTP opening, which leads to increased cellular levels of reactive oxygen species (ROS) that subsequently cause increased susceptibility of breast cancer cells to apoptosis." (PMID 32024968, 2020). "Low nuclear and cytoplasmic expression of Cdk5 is associated with poor breast cancer‐specific survival of breast cancer patients; in addition to survival, Cdk5 expression was associated with a number of clinicopathological criteria indicative of poor prognosis." (PMID 32352232, 2020). "If Cdk5 expression is directly linked with protein activity in breast cancer, then this study indicates that a Cdk5 inhibition strategy may not be appropriate." (PMID 32352232, 2020). "The activation of CDK5 signaling has been implicated in the control of cell motility and metastatic potential, which are significantly correlated with several markers of poor prognosis in breast cancer." (PMID 29325547, 2018). "With regard to prognostic implications, decreased expression of CDK5 was associated with advanced clinical stage and poor survival in gastric cancer patients and increased CDK5 expression was correlated to high pathological grading in breast cancer." (PMID 26860827, 2016). "Moreover, our previous study revealed that abnormal activation of miR-21/CDK5 axis was associated with breast cancer lymph node metastasis." (PMID 26690371, 2015). "Previous studies demonstrated that CDK5 overexpression was implicated in the tumorigenesis and aggressiveness in several malignancies, for instance lung, pancreatic, neuroendocrine thyroid, and breast cancer." (PMID 26205145, 2015). "In brain metastases originating from breast cancer, astrocytes induce tumor cells to overexpress the neuron-specific cyclin-dependent kinase 5 (Cdk5)." (PMID 41219968, 2025). "Cdk5 has been identified as a key regulator of this process in breast cancer cells stimulated with transforming growth factor beta 1 (TGF-β1), a major inducer of EMT." (PMID 41369365, 2025). "On one hand, it is documented that repression of CDK5RAP1, an inhibitor of cyclin-dependent kinase 5 activity, forces malignant melanoma and human breast cancer cell lines to undergo apoptosis." (PMID 38276004, 2024). "CDK5 and p35 are highly expressed in breast cancer tissues and positively correlate with tumor progression and poor prognosis." (PMID 37993880, 2023). "Similar to breast cancer, CDK5 activity is required to control cell motility and the metastatic potential of prostate cancer cells." (PMID 37993880, 2023). "In fact, TGFβ was shown to induce CDK5 and p35 expression while promoting epithelial–mesenchymal transition in breast cancer cells." (PMID 37377891, 2023).